VEGFA (vascular endothelial growth factor A)
Diseases named in the same sentence as VEGFA in open-access papers (continued):
Sharing a sentence is not in itself a finding about the gene and the disease.
tumor (continued). "In our previous study, we assessed the effect of LF on HT29 cells both in vitro and in vivo, and found that LF effectively suppressed angiogenesis in HT29 tumor by regulating the VEGFR2/VEGFA/PI3K/Akt/Erk1/2 pathway." (PMID 34131514, 2021). "As we know, high expression of VEGFA facilitates tumor growth and metastasis by promoting angiogenesis." (PMID 34306080, 2021). "Our study showed that VEGFA was the core of these hub genes, which further validated its important role in tumour deterioration and development." (PMID 34112125, 2021). "The high cell density of TAM in GBM is caused by a variety of factors secreted by the tumor cells that can attract TAM, namely CCL2, CX3CL1, CXCL12, CSF1, or VEGFA." (PMID 34359800, 2021). "Serum biomarkers of tumor angiogenesis, including vascular endothelial growth factor-A (VEGF-A), angiogenin, and angiopoietin-1, were measured by enzyme-linked immunosorbent assays simultaneously." (PMID 33794813, 2021). "Hypoxic tumor cells secrete vascular endothelial growth factor A (VEGFA), which binds to VEGF receptor 2 (VEGFR2) that is expressed on neighboring vascular endothelial cells, promoting tumor angiogenesis." (PMID 33921986, 2021). "The continuous expression of VEGF-A (vascular endothelial growth factor A) at high levels over long periods during tumor growth mediates the development of exiting new blood vessels to more stable forms." (PMID 33499069, 2021). "Among many predicted targets, VEGFA drew our attention because VEGFA is reported to be involved in tumor progression, we therefore selected VEGFA as a candidate target for further investigation." (PMID 34977016, 2021). "Studies have confirmed VEGFa is highly expressed in various tumours in the liver, breast, colon and melanoma cancer." (PMID 34765545, 2021). "For patients having high initial tumour load, Bevacizumab (a recombinant humanized monoclonal IgG1 antibody that targets vascular endothelial growth factor-A (VEGF-A)) is used." (PMID 34452625, 2021). "We observed increased expression of 5 immune suppressive genes including PVR (CD155), TGFB1, NT5E (CD73), VEGFA, and CD276 (B7-H3) in 9p21-loss tumors across multiple tumor types/subtypes when compared to 9p21-WT tumors." (PMID 34556668, 2021). "Once in the blood vessel, vascular endothelial growth factor A (VEGFA) signaling from TIE2+ perivascular macrophages causes vascular leakiness, allowing tumor cell egress." (PMID 34803925, 2021). "Collectively, these results suggest that OTX015 alters the stem-like properties of EPN cells, counteracting the expression of pro-invasive (CD133) and pro-angiogenetic (VEGFA) factors that mediate the interaction of cells with the tumor microenvironment." (PMID 33668642, 2021). "ANGPT2 and VEGFA have complementary roles in regulating tumor angiogenesis and synergistic effect on survival, suggesting that dual pathway inhibition is necessary to improve treatment outcomes." (PMID 31892982, 2020). "The treatment of xenografted mice with a specific monoclonal VEGFA antibody demonstrated that VEGFA was a strong in vivo pro-angiogenic factor and that its blockade suppressed tumor growth." (PMID 32545380, 2020). "In turn, upregulation of Zeb1 in tumor cells increases VEGFA production and reciprocally induces endothelial Jag1 to create a positive feedback loop." (PMID 33046710, 2020). "VEGFA, as one of the most recognized and effective endothelial growth factors, mobilizes the endothelial progenitor cells to participate in tumor angiogenesis." (PMID 33145353, 2020). "In conclusion, we confirmed that VEGFA, COX2 and HUR genes are overexpressed in RC tissue and pre-treatment VEGFA expression is higher in patients with tumor T-stage downstaging, highlighting their role in RC pathogenesis and predictive potential." (PMID 32331433, 2020). "These preclinical and clinical observations highlight the significant role of HIF-1-independent regulation of VEGFA and angiogenesis in tumor progression." (PMID 33351793, 2020).
tumor (continued). "Hypoxia (HIF1A) and VEGFA are pro-angiogenic leading to endothelial cell proliferation and formation of new blood capillaries to provide nutrients for tumor growth and metastasis." (PMID 33363037, 2020). "Although sunitinib and anti-VEGFA decreased tumor volume, invasiveness, hypoxia and EMT markers are increased." (PMID 32775327, 2020). "IHC staining showed that emodin was able to promote SerRS expression in tumor tissues and decrease VEGFA expression, resulting in the greatly blocked tumor angiogenesis shown by CD31 staining." (PMID 32550907, 2020). "Inflammation and hypoxia are characteristics of the tumor microenvironment, but they also promote VEGFA secretion in cancer cells." (PMID 33145353, 2020). "As a result, miR-134 was introduced as a tumor suppressor via attenuating VEGFA/VEGFR1 signaling to decrease OS progression and angiogenesis." (PMID 32565738, 2020). "It has been demonstrated that TANS favor the tumor proliferation and invasion by the secretion of cytokines as oncostatin M and vascular endothelial growth factor A (VEGF-A) and by elastase action." (PMID 32982967, 2020). "Tumor-adjacent tissue also presented elevated VEGFA protein levels compared to the normal tissues (p = 0.0138)." (PMID 32824922, 2020). "The capacity of IR to induce TGF-β signaling and vascular endothelial growth factor A (VEGFA) secretion in the tumor environment favored the expansion of Treg cells." (PMID 32612950, 2020). "Many studies on human malignant neoplasms have reported that HIF-1α and VEGFA induce tumor angiogenesis." (PMID 32382013, 2020). "This barrier has been observed in chemotherapy and is reversed by normalizing the tumor vasculature via deletion of myeloid-derived VEGFA and it also should be considered in ICIs." (PMID 32508809, 2020). "Vascular endothelial growth factor A (VEGF-A) plays essential roles in OSCC tumor angiogenesis and metastasis." (PMID 33330077, 2020). "bFGF and VEGFA have been identified as key mediators of tumor angiogenesis, and overexpression of bFGF and VEGF has been found in a variety of human cancers." (PMID 32527320, 2020). "In 1993, a monoclonal neutralizing antibody against VEGFA was reported to inhibit tumor growth in a xenograft model." (PMID 32138216, 2020). "We observed that VEGFA overexpression in TPT1-AS1-silenced HCT116 cells markedly reversed the decreased the subcutaneous tumor growth and CD31 expression in tumors, and vice versa in SW480 cells (Figure 4Bi and 4Bii)." (PMID 32248186, 2020). "In lung cancer cells, lncRNA F630028O10Rik reduces angiogenesis by inhibiting VEGFA secretion and tumor growth." (PMID 32993787, 2020). "Several angiogenic and anti-angiogenic factors, including basic fibroblast growth factor (bFGF) and vascular endothelial growth factor A (VEGFA), regulate tumor angiogenesis." (PMID 32527320, 2020). "Taken together, above results strongly indicated that B7-H3 promoted tumor angiogenesis in a manner mainly dependent on the NF-κB/VEGFA signaling pathway in CRC." (PMID 31974361, 2020). "VEGFA (Vascular endothelial growth factor-A) is a primary factor driving expansion of the tumor vascular bed." (PMID 32600379, 2020). "Among eight significantly downregulated miRNAs, miR-126 acts as tumor suppressor by decreasing the translation of vascular endothelial growth factor-A (VEGF-A) mRNA." (PMID 36046389, 2020). "In this regard, our study has demonstrated that angiogenic growth factors (VEGFA) and hypoxia are closely related to the PD-L1 expression on VECs in tumor." (PMID 32366856, 2020). "In tumor cells, the VEGFA-VEGFR2 binding activates autocrine survival and migration signaling in angiogenesis independent manner." (PMID 32346056, 2020). "Our data suggest that miR-299-3p is frequently downregulated in PCa cells and tissues and exerts a tumor suppressor role through the bimodal targeting of AR and VEGFA to inhibit different signaling cascades that are constitutively active in PCa." (PMID 32198489, 2020).
tumor (continued). "Tumor tissues with high expression of TPT1-AS1 tended to show high levels of VEGFA expression in both clinical samples and xenograft tumors, and vice versa." (PMID 32248186, 2020). "Stably transfected 786-O cells were inoculated into nude mice in order to explore the effects of lncRNA IRAIN and VEGFA on tumor growth of RC in vivo." (PMID 32983957, 2020). "Vascular endothelial growth factor A (VEGF-A) is one of the major regulatory factors of tumor angiogenesis." (PMID 33746736, 2020). "Although the correlation between the expression of VEGFA and tumor size or the development of distant metastasis is frequently analyzed in patients with UM, the exact function of VEGFA is still not established." (PMID 33255843, 2020). "At the 3-week end point, the vasculature in tumor xenografts was examined by western blot analysis and immunostaining to detect VEGFA and endothelial cell marker VE-Cadherin (Cdh5)." (PMID 33351793, 2020). "On the other side, tumor-released VEGFA, semaphorin 3A and CXCL12 recruit TAMs in pre metastatic niches, where they suppress the cytotoxic activity of CD8+ T cells and promote recruitment of Treg cells." (PMID 32397392, 2020). "Overactive angiogenesis is a marker of malignant tumors, and VEGFA induces neovascularization and promotes tumor growth and metastasis." (PMID 32148531, 2020). "Several studies have demonstrated that VEGF-C and VEGF-D can promote angiogenesis and tumor progression even when VEGFA activity is suppressed." (PMID 32993787, 2020). "Taken together, we propose a model that describes the bimodal action of miR-299-3p as a tumor suppressor in PCa by targeting both AR and VEGFA simultaneously." (PMID 32198489, 2020). "In a cohort of 299 GC patients, the expression of MMP-2, MMP-9, and VEGFA positively correlated with the tumor size, invasive depth, lymphatic and venous invasion, lymph node metastasis and staging." (PMID 32456248, 2020). "Positive expression of TNS4 and VEGFA was detected in 6.7% and 5.2% (n = 134) of adjacent non-malignant tissues, respectively, and the positive rates of TNS4 and VEGFA in tumour tissues were 50.7% and 32.1% (n = 134), respectively." (PMID 32732965, 2020). "In the BxPC-3 xenograft model here, the VEGFA-and-NRP1 dual-targeting bispecific antibody (IDB0076) significantly retarded the tumor growth and tumor blood vessel formation as compared with the VEGFA-blocking monospecific antibody bevacizumab." (PMID 32560565, 2020). "The establishment of stable gradients through the binding with ECM molecules impacts on the activity of the key angiogenic factor VEGFA, which, depending on its concentration, can regulate various aspects of tumor angiogenesis." (PMID 32456248, 2020). "LncRNA IRAIN was also able to suppress RC tumor growth via repression of VEGFA in an in vivo mouse xenograft model." (PMID 32983957, 2020). "These cells can induce an immunosuppressive microenvironment and are associated with cytokines such as TNFα, VEGFA, and IL8, and accumulate in hypoxic regions of the tumor." (PMID 33228231, 2020). "Combination blockade of VEGFA and angiopoietin-2 normalized tumor blood vessels and increased lymphocyte infiltration, improving outcomes when combined with anti-PD-1 in B16-OVA and MC38 mouse models." (PMID 32133005, 2020). "In these hypoxic regions, APLN is co-expressed with VEGFA, suggesting a cooperative function of apelin and VEGFA in paracrine signaling from tumor to endothelial cells during GBM angiogenesis." (PMID 32545380, 2020).
tumor (continued). "All invasive area cells (mixed unsorted, 5-ALA negative, and 5-ALA positive) showed low expression levels of VEGFA compared to tumor core and rim regions." (PMID 32904996, 2020). "Patients with overexpression of VEGFA are prone to have larger tumor volumes, vascular hyperpermeability, and hemorrhage." (PMID 33362712, 2020). "By supplying oxygen and nutrients to the tumors, it is well established that VEGFA enhances tumor progression." (PMID 32377503, 2020). "The binding process of the angiogenic activator VEGFA produced by tumor cells to its receptor VEGFR on endothelial cells activates several nuclear signaling cascades and promotes endothelial cell proliferation." (PMID 32896063, 2020). "VEGFA is involved in the regulation of various tumor angiogenesis (such as lung squamous cell carcinoma, ovarian cancer, etc.)." (PMID 32600379, 2020). "This points toward development of a less-aggressive phenotype as a result of cultivation on the RPM, as VEGFA has been implicated in pathological angiogenesis and tumor development, while NGAL induces VEGFA expression, among other cancer-promoting functions." (PMID 32070055, 2020). "MiR-26a significantly impaired in vivo tumor angiogenesis by inhibiting VEGFA production through HGF/c-Met axis in HCC cells." (PMID 32083078, 2020). "It has been demonstrated that lncRNA PVT1 is involved in the high microvessel density in gastric cancer as well as the promotion of tumor growth through activation of the STAT3 signaling pathway as well as secretion of VEGFA." (PMID 32190702, 2020). "The main chemo-attractants for EPCs in tumor tissue are VEGFA and SDF1, released by ECs, cancer cells and CAFs." (PMID 32775327, 2020). "On the other hand, siCXCL2 OmAd-CM significantly decreased VEGFA expression in the tumour compared to siNT OmAd-CM." (PMID 32439934, 2020). "Knockdown of DLX6-AS1 shows tumor inhibition effect, which can be reversed by miR-195-5p inhibitor or VEGFA overexpression." (PMID 32756011, 2020). "Both KSP and VEGFA are highly expressed in a variety of tumor types, where VEGF is proposed to modulate tumor angiogenesis or the growth of blood vessels to supply nutrients to tumors, and KSP is essential for mitotic spindle formation in proliferative cells." (PMID 33036435, 2020). "VEGFA has a mitogenic effect on vascular endothelial cells, stimulating endothelial tube formation and neovascularization of the tumor." (PMID 32318345, 2020). "Silencing SIRT2 significantly suppressed tumor angiogenesis by inhibiting the STAT3/VEGFA signaling pathway in CRC cells." (PMID 31974361, 2020). "The other factor was TRPV1 downregulation aberrantly correlated with PTEN (r = -0.206, P = 1.63e-06), a classic tumor suppressor, and VEGFA (r = -0.493, P = 0e+00), which is widely viewed as a promoting gene of ccRCC." (PMID 32913462, 2020). "Increased SDF-1α in NF-PitNETs inhibits miR-134 effect on VEGFA and plays an important role in tumor cell growth and invasiveness of NF-PitNETs." (PMID 33362712, 2020). "We first examined the expression levels of VEGFA from several tumor cell lines for selecting tumor cells with the highest angiogenic activity for xenotransplantation." (PMID 32131390, 2020). "In the development of solid tumor, basic fibroblast growth factor (bFGF) and vascular endothelial growth factor A (VEGFA) can promote tumor progression and angiogenesis in autocrine and paracrine manners." (PMID 32944017, 2020). "It is common knowledge that VEGFA has tumor-promoting properties by facilitating cell proliferation and migration." (PMID 32983957, 2020). "Bevacizumab is a vascular endothelial growth factor A (VEGFA) monoclonal antibody which attenuates VEGFA dependent tumor blood vessels formation and inhibits tumor angiogenesis and has been used for the treatment of MPE." (PMID 31726490, 2020).
tumor (continued). "In previous studies, it was found that HIF-1α was notably stabilized in malignant tumor cells under hypoxic conditions, along with upregulating its target gene, VEGFA, which is considered the principal inducer of angiogenesis." (PMID 32273947, 2020). "The IHC assays indicated that the levels of Ki67 and VEGFA were obviously increased in the miR‐223‐OV tumor tissues and were downregulated in the miR‐223‐KD tumors." (PMID 32491253, 2020). "VEGFA was introduced as a poor prognostic marker for tumor-free survival in OS, suggesting its potential for anti-VEGF therapy." (PMID 32565738, 2020). "Tumor cells grow rapidly and are hypoxic in nature, and secrete vascular endothelial growth factor A (VEGFA)." (PMID 31936832, 2020). "Tissues with bigger tumor size (T3-T4) had increased VEGFA expression than those with smaller tumor size (T1-T2) (P=0.0346)." (PMID 31892982, 2020). "Bevacizumab, an anti-angiogenic inhibitor targeting VEGFA, is approved to treat several tumor types, including TNBC8." (PMID 32944400, 2020). "HIF1α is another key regulator of tumor growth and angiogenesis as a transcriptional regulator of VEGFA." (PMID 32070413, 2020). "As a consequence, SDF-1α inhibited the expression of the tumor suppressor gene miR-134 by promoting the expression of miR-134 target gene VEGFA to stimulate the proliferation and invasion ability of αT3-1 cells." (PMID 33362712, 2020). "Major studies showed that DA acting via D2R inhibits tumor angiogenesis by suppressing the actions of vascular permeability factor/vascular endothelial growth factor A on tumor endothelial cells and bone marrow-derived endothelial progenitor cells." (PMID 33147760, 2020). "Nestin+/NG2+ “Type‐2” pericytes contribute to tumour angiogenesis by promoting ECs survival through their secretomes including VEGFA, ANGPT1 and ECM components." (PMID 32588948, 2020). "Consistently, both the quantitative PCR and immunoblotting revealed decreased VEGFA expression in PyMT;Zeb1cKO tumor cells compared to that in PyMT cells." (PMID 33046710, 2020). "There is significant evidence that the VEGFA gene alternative RNA splicing plays an important role in tumor growth and progression, suggesting a potential target for new cancer therapies." (PMID 33035235, 2020). "In the tumor microenvironment, M2 macrophages play critical roles in the process of angiogenesis through the secretion of VEGFA, epidermal growth factor, and interleukin-8." (PMID 32075061, 2020). "VEGFA plays important roles not just in angiogenesis but in tumor growth, metastasis, and survival as well; that is why VEGFA is upregulated in tumors and necessary for tumor survival." (PMID 33224312, 2020). "Nevertheless, researchers have shown that VEGFR1 is significantly overexpressed in distant metastatic ovarian cancer which suggests an important role for the VEGFA/VEGFR1 signaling in the tumor's ability to spread." (PMID 32377503, 2020). "Pro-EGCG such as octaacetate or peracetate-protected EGCG suppressed xenograft tumor growth, inhibited tumor angiogenesis, and reduced the expression of vascular endothelial growth factor A (VEGFA) and HIF1α by the PI3K/AKT/mTOR signaling pathway." (PMID 33113766, 2020). "Analysis of RNA gene expression of VEGFA in tumour tissues at 13 weeks, which is the early phase of tumour development, indicated that VEGFA expression was significantly higher in the siNT OmAd-CM-treated GC tumour than in the control GC tumour." (PMID 32439934, 2020). "Only in some studies has an inverse correlation between ADAMTS expression and tumor microvessel density or VEGFA expression been clearly described." (PMID 32456248, 2020). "Then, it was searched in GEPIA that VEGFA expression was correlated with different tumor stages of COAD." (PMID 32700743, 2020).